UCP2 (uncoupling protein 2)
Diseases named in the same sentence as UCP2 in open-access papers (continued):
Sharing a sentence is not in itself a finding about the gene and the disease.
Sepsis (27 papers, 2010 to 2025). Sepsis is defined as life-threatening organ dysfunction caused by a dysregulated host response to infection. "Fatty acid synthase upregulation by bNOS can cause activation of NLRP3 inflammasome during sepsis through the mitochondrial uncoupling protein-2 which is considered as a potential therapeutic target for inflammatory diseases." (PMID 26388860, 2015). "Compared with the controls, sepsis caused a 1.4-fold increase in UCP2 mRNA levels and a 1.3-fold increase in UCP2 protein levels following treatment with LPS/PepG or saline (P<0.05)." (PMID 25873251, 2015). "Silencing UCP2 further intensifies the Warburg effect, while overexpression of UCP2 restricts glycolysis and inhibits the expression of oxidases, thereby alleviating the damage caused by sepsis." (PMID 38429403, 2024). "This led the researchers to propose that UCP2 in blood cells could serve as a specific biomarker for sepsis, with its expression levels being positively associated with the severity of the disease." (PMID 38429403, 2024). "Knocking out UCP2 aggravates the destruction of mitochondrial ultrastructure and causes more severe edema to the mitochondrial inner membrane under septic conditions, hinting the positive role of UCP2 in sepsis." (PMID 37101253, 2023). "Additionally, increased myocardial protein expression of UCP2 was observed in a canine and rat model of endotoxin-induced sepsis associated with decreased phosphocreatine/ATP ratios." (PMID 31182990, 2019). "This investigation was aimed at determining the role of UCP2 in the heart during sepsis and to test the therapeutic potential of targeting this gene with a cardiotropic adenoassociated viral vector encoding shRNA for UCP2 using a mouse model of LPS-induced sepsis." (PMID 31080837, 2019). "Additionally, the expression of UCP2 can be directly elevated by pyruvate, the intermediate product of lactate, which is strongly associated with sepsis." (PMID 28428961, 2017). "Therefore, the purpose of the present study was to confirm the potency of the effects of GIK using a rat model of intestinal mucosal barrier injury and to elucidate the association between GIK therapy and the expression of UCP2 in a CLP-induced sepsis model." (PMID 28428961, 2017). "Research on the association between UCP2 and mtDNA in sepsis is limited, and the possible explanation of our finding is that the silencing of UCP2 through the alteration in ROS production, uncoupling activity and MMP, eventually leads to the deletion of mtDNA under septic conditions." (PMID 25873251, 2015). "However, in a sepsis-associated astrocyte model, UCP2 was found to protect mitochondria, which may play a protective role in SAE." (PMID 36699054, 2022). "However, the role of UCP2 in sepsis and the underlying mechanisms remain to be further explored." (PMID 31080837, 2019). "Our protein analysis indicated that UCP2 was elevated in patients with severe sepsis and imatinib-treated patients." (PMID 40524944, 2025). "This review aims to elaborate on the potential therapeutic effect of overexpressing UCP2 on sepsis from the perspective of metabolic and immune regulation." (PMID 38429403, 2024). "Our research indicates that overexpression of UCP2 reduces the Warburg effect, restores mitochondrial function, and improves the prognosis of sepsis." (PMID 38429403, 2024). "The results revealed that both the mRNA and protein expressions of UCP2 were significantly higher in the blood cells of sepsis patients compared to healthy volunteers." (PMID 38429403, 2024). "Recent research has demonstrated that UCP2 not only serves as a critical target in sepsis but also functions as a key metabolic switch involved in immune cell-mediated inflammatory responses." (PMID 38429403, 2024). "UCP2, as a potential therapeutic target for sepsis, is not only widely expressed in immune cells but also involved in metabolic regulation." (PMID 38429403, 2024).
Sepsis (continued). "This article focuses on UCP2 as a target and discusses metabolic reprogramming during sepsis and the complex regulatory mechanisms between different stages of inflammation." (PMID 38429403, 2024). "UCP2 plays a positive role during sepsis, regulating the shift from OXPHOS to glycolysis and inhibiting damage caused by high levels of glycolysis." (PMID 38429403, 2024). "Its varied expression levels in sepsis are associated with different roles, and more researchers believe that overexpression of UCP2 plays a positive role in sepsis." (PMID 38429403, 2024). "It was demonstrated that UCP2 protected mitochondria and alleviated oxidative stress in LPS-induced renal injury in sepsis." (PMID 36699054, 2022). "Then UCP2 knockdown further activated autophagy and protected cardiac function and improved survival rate during sepsis." (PMID 31080837, 2019). "Our result suggests a signaling pathway from UCP2 to autophagy that protects cardiac mitochondria and cardiac function during sepsis." (PMID 31080837, 2019). "The present study showed no alteration of mitochondrial conductance to protons in spite of an increase in non-coupled (with phosphorylation) respiration and increasing level of UCP2 mRNA in the time course sepsis." (PMID 30187255, 2018). "Our findings suggested that UCP2 is crucial for protecting against sepsis-induced cardiomyopathy by promoting cardiomyocytes survival through autophagy induction." (PMID 29547569, 2018). "Cells dealing with a specific inhibitor genipin had been severely attacked in the LPS model, indicating UCP2 can be the protector during sepsis." (PMID 29547569, 2018). "Our results demonstrated that UCP2 blocking can bring catastrophic injuries to myocardial cells in sepsis, which was similar to precious study." (PMID 29547569, 2018). "UCP2, a mitochondrial inner membrane protein, is capable of regulating cell metabolism of carbohydrates and lipids that have central roles in sepsis or ischemia/reperfusion diseases." (PMID 28428961, 2017). "It is reported that the expression of UCP2 is elevated during sepsis and is adjusted by acetyl-CoA and pyruvate; the latter is the intermediate product of glucose metabolism and can produce lactate." (PMID 28428961, 2017). "Consistently, mouse macrophage fatty acid synthase is induced during sepsis in a mechanism depending on the mitochondrial uncoupling protein 2 (UCP2)." (PMID 28533780, 2017). "In the past, UCP2 was considered to be a protective factor providing resistance to sepsis or ischemia/reperfusion diseases." (PMID 28428961, 2017). "In this study, fenofibrate induces SHP expression and increases survival in an animal model of sepsis by increasing the expression of mitochondrial uncoupling protein 2 (UCP2)." (PMID 26504773, 2015). "In the present study, the silencing of UCP2 by siRNA was associated with a relative increase in ROS production and a significant rebound in MMP during sepsis, which is consistent with uncoupling mechanisms." (PMID 25873251, 2015). "Our present finding that the silencing of UCP2 leads an increase in MMP and ROS production during sepsis suggests that UCP2 plays a protective effect in septic cardiomyocytes." (PMID 25873251, 2015). "Uncoupling proteins (UCPs) have been implicated in sepsis where UCP3 has been shown to be upregulated in muscle in a CLP model in rats and UCP2 deficient mice were protected from LPS-induced liver failure." (PMID 21106065, 2010). "UCP2 in blood cells may serve as a specific biomarker for sepsis, and its level is positively correlated with the severity of sepsis." (PMID 40504881, 2025). "UCP2 not only serves as a key mediator in the pathogenesis of sepsis, but it also acts as a “metabolic switch” connecting glucose oxidation and mitochondrial metabolism, promoting the oxidation of glutamine and fatty acids instead of glucose-derived pyruvate oxidation." (PMID 38429403, 2024).
Sepsis (continued). "Therefore, we will first start with the physiological and biochemical aspects of UCP2 to better understand its role in sepsis." (PMID 38429403, 2024). "UCP2 serves as a key factor in the metabolic regulation of sepsis." (PMID 38429403, 2024). "UCP2, a mitochondrial transporter protein uncoupling oxidative phosphorylation from ATP synthesis, was upregulated in the heart, liver, and other tissues of septic models, and showed a protective effect on mitochondrial injury in sepsis." (PMID 32997405, 2020). "Increasing studies reported that cardiac UCP2 expression was increased in animal models of sepsis." (PMID 31182990, 2019). "These novel findings clearly suggest that UCP2-regulated autophagy might play a crucial role in the process of sepsis, which possesses a therapeutic potential for sepsis." (PMID 31080837, 2019). "Previous study reported that UCP2 in blood cells of sepsis patients was significantly higher than that of healthy controls and the expression level of UCP2 in blood cells of sepsis patients was significantly reduced after treatment, compared to that before treatment." (PMID 31080837, 2019). "UCP2 level in blood cells might be a specific biomarker for sepsis, which is positively correlated with the severity of sepsis." (PMID 31080837, 2019). "Until now, we speculate that UCP2 is crucial for protecting against sepsis-induced cardiomyopathy by promoting cardiomyocytes survival through autophagy induction and apoptosis reduction." (PMID 29547569, 2018). "Precious studies had illustrated that UCP2 can be up-regulated in sepsis." (PMID 29547569, 2018). "To further explore and confirm whether UCP2 had effect on sepsis-induced cardiomyopathy, we use UCP2 knocked out animal model in vivo and genipin to be the UCP2 specific inhibitor in vitro like other research." (PMID 29547569, 2018). "Uncoupling protein 2 (UCP2) may be critical for intestinal barrier function which may play a key role in the development of sepsis, and insulin has been reported to have anti-inflammatory effects." (PMID 28428961, 2017). "UCP2 may be upregulated by high glucose stress and glucose and lipid metabolites, which are always elevated during sepsis." (PMID 28428961, 2017). "The present study demonstrates that GIK protects intestinal mucosal barrier function in CLP-induced sepsis and that UCP2 and the NLRP3/caspase-1/IL-1β signaling pathway may be involved in this process." (PMID 28428961, 2017). "Given its central role in regulating mitochondrial ROS production and cellular energy transduction, we hypothesized that UCP2 may play a protective role in sepsis." (PMID 25873251, 2015). "Therefore, the effect of UCP2 on lung injury in sepsis requires further studies." (PMID 40524944, 2025). "Numerous studies showed that UCP2 involved the regulation of inflammation, regulation of oxidative stress, maintenance of mitochondrial membrane potential, and energy production, which may be related to the pathophysiology of sepsis." (PMID 31080837, 2019). "The findings of these studies imply that UCP2 may have adverse effects on survival during sepsis." (PMID 28428961, 2017). "Nonetheless, whether UCP2 plays a protective role in sepsis needs to be determined." (PMID 25873251, 2015). "UCP2, which appears mainly in innate immune cells, has higher expression in sepsis patients compared with non-sepsis patients." (PMID 35847986, 2022). "Of the novel genes, UCP2 is highly down-regulated in treatment failures compared to cures at pre-treatment baseline and has been shown to be involved in fatty acid metabolism that promotes NLRP3 inflammasome activation during sepsis." (PMID 29050771, 2017). "Hence, we suggest OA enhance UCP2, reducing ROS production and increasing fatty acid oxidation, thus lowering plasma NEFA during experimental sepsis." (PMID 27078880, 2016).
Sepsis (continued). "This study proved that the levels of SIRT1, PGC-1α, UCP2, TFAM, and COXIV all decreased in septic mice, the effect of which was reconciled by nanoFe treatment (vs. the CLP group, B P < 0.05), indicating the positive role of nanoFe in improving mitochondrial biogenesis during sepsis." (PMID 36064371, 2022). "Increased expression of UCP2 may enhance inflammatory responses in ALI and sepsis." (PMID 27057102, 2016).
colon carcinoma (25 papers, 2009 to 2025). "A drug-resistant subset of cancer cells derived from leukemia, melanoma, and colon cancer cells exhibited increased levels of UCP2 and diminished susceptibility to cytotoxic effects." (PMID 22292025, 2012). "In fact, UCP2 has been connected to metabolic rewiring, as it is upregulated in human colon cancer in response to oxidative stress and could be associated with tumor progression, so it is expected that cancer cells rely on this protein to maintain their aggressiveness." (PMID 38132283, 2023). "UCP2 is frequently overexpressed in a range of malignancies, including breast cancer, leukemia, colon cancer, and thyroid tumors." (PMID 40983641, 2025). "On the other hand, UCP2 was upregulated in established colon cancer induced in an APC−/+ mice model and in human colon cancer samples from stage II and stage III cases compared to adjacent normal tissue." (PMID 39795950, 2024). "UCP2 deletion contributes to an increased number of colon tumors and a reduced survival rate in mice when exposure to azoxymethane (AOM) followed by addition of dextran sodium sulfate (DSS) treatment." (PMID 35090503, 2022). "The mRNA expression level of UCP2 gene was assessed in colon cancer and they found that UCP2 gene was upregulated in colon cancer tissue samples than in its adjacent tissue samples." (PMID 32548056, 2020). "Previous studies indicate that mitochondria uncoupling protein 2 (UCP-2) is involved in the development of chemotherapy resistance in colon cancer and lung cancer cells." (PMID 26107945, 2015). "Cisplatin downregulated the expression of UCP2 in colon cancer cells, suggesting that UCP2 over-expression is involved in the development of a variety of cancers." (PMID 24027528, 2013). "Other stimuli of UCP expression/activity are hydrogen peroxide as shown for UCP5 in colon cancer cells and gemcitabine chemotherapy as reported for UCP2 in pancreatic, lung and bladder cancer cell lines." (PMID 23966948, 2013). "In human colon cancer, UCP2 mRNA and protein expression reportedly is increased by factor of 3–4 as compared to peritumoral normal epithelium." (PMID 23966948, 2013). "Over-expression of UCP2 in colon cancer cells also inhibits ROS accumulation and apoptosis after exposure to chemotherapeutic agents." (PMID 21935467, 2011). "Chromanes inhibit basal proton conductance of UCP1 and UCP2 and sensitise HT-29 colon cancer cells to commonly used chemotherapeutic agents such as cisplatin and doxorubicin." (PMID 21712825, 2011). "UCP2 overexpression has been described in various types of cancer including leukemia cells, human colon cancer cells, thyroid tumours, and hepatomas." (PMID 20967268, 2010). "For instance, overexpression of UCP2 in HCT116 human colon cancer cells diminishes the pro-apoptotic effects of the chemotherapeutics, etoposide and doxorubicin." (PMID 20967268, 2010). "Colon cancers exhibit increased UCP2 expression, which, through lowering intracellular ROS levels, confers reduced susceptibility to oxidative damage, apoptosis and drug-resistance." (PMID 19564950, 2009). "Inhibition of UCP2 enhanced the cisplatin-induced cytotoxicity in colon cancer cells." (PMID 26666173, 2015). "It was evidenced that overexpression of UCP-2 in colon cancer cells could promote their resistance to topoisomerase I inhibitor CPT-11, Gemcitabine and Doxorubicin treatment." (PMID 26107945, 2015). "Similarly, overexpression of UCP2 in a human colon cancer cell line has been shown to blunt topoisomerase I inhibitor CPT-11-induced accumulation of reactive oxygen species and apoptosis in vitro and to confer CPT-11 resistance of tumor xenografts." (PMID 23966948, 2013).
colon carcinoma (continued). "Although UCP2 over-expression has been described in various types of cancer, including human colon cancer cells, thyroid tumor, and hepatocellular carcinoma, the precise function of UCP2 in cells remains unknown." (PMID 22292025, 2012). "Moreover, xenografts of UCP2-overexpressing HCT116 colon cancer cells retain growth in nude mice receiving chemotherapy, providing strong evidence that UCP2 upregulation is a plausible mechanism of chemoresistance in such studies." (PMID 21712825, 2011). "Interestingly, UCP2 expression has been shown to be increased in several hepatocellular cancer and cell lines, oxyphilic thyroid tumors and human colon cancer." (PMID 24281083, 2010). "Thus, UCP2 expression is increased in human colon cancer and may correlate with the degree of oxidative stress and neoplastic changes along with the ‘two-hit’ hypothesis and in the setting of adenoma–carcinoma transformation." (PMID 21712825, 2011). "The ability of UCPs to uncouple ATP synthesis from respiration and the fact that UCP2 is overexpressed in several chemoresistant cancer cell lines and primary human colon cancers have lead to speculate about the existence of a link between UCPs and the Warburg effect." (PMID 24281083, 2010). "In addition, UCP2 expression gradually increases during the colon adenoma-carcinoma sequence and is higher in clinical stages III and IV colon cancer than in stage I and II." (PMID 23966948, 2013). "UCP2 may fulfill this uncoupling role in cancer cells; other reports describe the expression of other uncoupling proteins, including UCP3 and UCP5 in adenocarcinoma and colon cancer cells." (PMID 20967268, 2010). "Uncoupling protein-2, a mitochondrial membrane protein, with an expression level that is significantly higher in colon cancer tissue than in adjacent non-cancerous tissue, may play a role in the development of colon cancer by negatively regulating the production of reactive oxygen species." (PMID 23226729, 2012).